EZH2 (enhancer of zeste 2 polycomb repressive complex 2 subunit)
Diseases named in the same sentence as EZH2 in open-access papers (continued):
Sharing a sentence is not in itself a finding about the gene and the disease.
breast cancer (continued). "Here, we choose three CTCF ChIP-seq experiments (HMEC + Broad + CTCF, HMEC + Broad + EZH2 and HMEC + UW + CTCF) and three DHS ChIP-seq experiments (MCF-7, MCF-7+Hypoxia_LacAcid, T-47D), all related to the breast cancer." (PMID 35672401, 2022). "miR-340 is a known TS miR in breast cancer and regulates metastasis in TNBC cells by inhibiting EZH2." (PMID 35615145, 2022). "For relapse-free survival, breast cancer patients with higher expression of VEGFA, EZH2, CASP3, WWP1, CUL2, and COL3A1 had poorer prognosis." (PMID 35812757, 2022). "Here, we report that the enhancer of zeste homolog 2 (EZH2) can promote the formation of CCF and activate the cGAS–STING pathway to promote breast cancer metastasis." (PMID 35163710, 2022). "To further test the regulation of miR-148a with HDAC2 and EZH2, we analyzed the expression levels of HDAC2, EZH2, and miR-148a in twenty pairs of human breast cancer tissues and their corresponding normal breast tissues." (PMID 35892859, 2022). "LINC01133 inhibits breast cancer invasion and metastasis through repressing SOX4 expression by recruiting EZH2 to SOX4 promoter." (PMID 33834618, 2021). "The metabolic enzymes EZH2 and MIF connected to deregulated metabolites L-lysine and citric acid were commonly regulated in breast cancer." (PMID 34790674, 2021). "Upregulation of EZH2 by Arg342 methylation consequently reduces the expression of EZH2 target genes such as HOXA10, DAB2IP, HOXA9, and HOXA7, promoting breast cancer cell migration and metastasis." (PMID 34006904, 2021). "Using breast cancer cell lines, we found that mutant forms of NOTCH1 or NOTCH2 collaborate with EZH2 to mediate the transcriptional repression of PTEN in these poor-prognosis breast cancers." (PMID 33750924, 2021). "We previously reported that both EZH2 and YY1 showed much lower expression in breast cancer cells than that in normal mammary cells, consistent with their important regulatory roles in mammary oncogenesis." (PMID 34065631, 2021). "We found that the EZH2 protein in tumor tissues of UCEC and LUAD were higher than the normal tissues, and the result of the breast cancer was the opposite (P < 0.001)." (PMID 34381492, 2021). "Recent studies showed that EZH2 has an essential role in maintaining CSC properties in multiple cancer types, including breast cancer, prostate cancer, and glioblastoma." (PMID 33966039, 2021). "A significant correlation with poor prognosis was also observed for high EZH2 and SUZ12 expression in sarcoma and in lung adenocarcinoma; for EZH2 in breast cancer; for EZH2 and EED expression in ovarian cancer." (PMID 34202528, 2021). "Activated AMPK has also been reported to disrupt the interaction between EZH2 and the suppressor of zeste 12 (SUZ12) by phosphorylating EZH2 in ovarian and breast cancer cells." (PMID 34815475, 2021). "Moreover, EZH2 could bind and epigenetically silenced miR-381 in breast cancer." (PMID 34806925, 2021). "In breast cancer cells, ZBTB4 transcriptionally suppresses the expression of EZH2 and inhibits the growth of cancer cells." (PMID 34047477, 2021). "LncRNA HOTAIR recruits EZH2 to specific target genes and induces the trimethylation of H3K27 and epigenetic silencing of genes that suppress breast cancer metastasis." (PMID 34257531, 2021). "Enhancer of zeste homolog 2 (EZH2) is a candidate oncogenic driver in diverse cancers, such as breast cancer." (PMID 34335938, 2021). "At the same time, overexpression of Flag-EZH2-R342K had little effect on the proliferation of MCF7 and MDA-MB-231 breast cancer cells." (PMID 34775498, 2021). "Following the response induced by chemotherapeutic agents in breast cancer cells, both DOX and PTX promoted the expression of EZH2 and STAT3 at 48 h after 4 h of drug treatment." (PMID 33823894, 2021).
breast cancer (continued). "In breast cancer cells, lncRNA ANCR binds EZH2 and also promotes the binding of CDK1 kinase to EZH2, which increases the phosphorylation of threonine Thr-345 and Thr-487 in EZH2, ultimately leading to the ubiquitination of EZH2." (PMID 34783641, 2021). "PcG of proteins, such as BMI1 (B lymphoma Mo-MLV insertion region homolog), a component of the PRC1, and EZH2 (PRC2), are upregulated in breast cancer and BCSCs." (PMID 34360879, 2021). "OGT-mediated O-GlcNAcylation of EZH2 attenuates EZH2 ubiquitination in breast cancer cell; PCAF-mediated EZH2-K348 acetylation inhibits CDK1 catalyzing pT345-EZH2 and pT487-EZH2 and increases EZH2 stability in lung cancer." (PMID 33308321, 2020). "Our research demonstrated that EZH2 was up‐regulated in breast cancer (BC) tissues and cells, whereas DLC1 was down‐regulated, and the expression of EZH2 and DLC1 was negatively correlated in BC." (PMID 32725802, 2020). "Our study has illustrated that EZH2-miR-29b/miR-30d-LOXL4 signaling pathway is critical for the proliferation and metastasis of breast cancer cells." (PMID 32754259, 2020). "Recent study showed that EZH2 is overexpressed in diverse human cancer tissues, such as HCC, breast cancer, PCa, lung cancer, gastric cancer, cervical cancer, lymphoma." (PMID 33194612, 2020). "EZH2 (Enhancer of Zeste 2), component of polycomb repressive complex (PRC2) is known for mediating breast cancer progression and metastasis via H3K27 tri-methylation." (PMID 32257110, 2020). "Metformin modulates the following axes: miR-miR-708/CD47 in breast cancer, miR-27b/ENPP1 in breast cancer, 26a/EZH2 in pancreatic cancer, and blocks TGFβ1-induced upregulation of miR-181a and downregulation of miR-96 in breast cancer." (PMID 32512882, 2020). "Suppressed autophagy on the account of miR-101 is reported in breast cancer (targeting RAB5A, STMN1 and ATG4D), HCC (through EZH2) and in ischemic liver (via activating mTOR signaling pathway)." (PMID 32124227, 2020). "In our study, we observed that LOXL4 expression was positively correlated with EZH2 expression and macrophage infiltration, evidenced by CD68 staining in human breast cancer tissues." (PMID 32754259, 2020). "In the current study, we demonstrated that blocking EZH2 activity by EZH2 inhibitors or EZH2 siRNAs significantly reduced the expression of LOXL4 associated with low H3K27me3 expression, suggesting that coordinated epigenetic silencing may exist in breast cancer cells." (PMID 32754259, 2020). "Inhibition of SAH hydrolase leads to the accumulation of SAH in MCF7 breast cancer and T24 bladder cancer cells, which finally inhibits the HMT activity of EZH2 and downregulates the level of H3K27me3." (PMID 32448308, 2020). "Enhancer of Zeste Homolog 2 (EZH2), a key epigenetic regulator, is involved in breast cancer progression and metastasis." (PMID 32754259, 2020). "According to a previous study, specific activation of AKT-1 is a contributor to EZH2-induced phenotype, and the overexpression of EZH2 induces activation of AKT-1 and BRCA1 inhibition in breast cancer, which was consistent with our findings." (PMID 31830649, 2020). "Based on the analysis of depleted gRNAs, we identified ERGs associated with cell cycle and cell senescence, and these ERGs showed higher rate of copy number amplification or up-regulation in breast cancer (i.e., ARID4B and EZH2)." (PMID 32963031, 2020). "Our study identified an important transcriptional axis comprised of EZH2, miR-29b/miR-30d, and LOXL4, which participated in driving the development of breast cancer by regulating macrophage activation." (PMID 32754259, 2020). "In breast cancer MCF7 cells, a co-regulation by OGT and EZH2 was also evidenced for 16 tumor suppressor genes including UNC5A." (PMID 33126652, 2020). "A positive correlation between EZH2 and LOXL4 expression was also detected in breast cancer patient samples." (PMID 32754259, 2020).
breast cancer (continued). "We also demonstrated that tumor-associated maceophages (TAMs) facilitate PRMT1-mediated R342-EZH2 ADMA methylation by secreting IL-6, which strengthens EZH2 protein stability and enhances breast cancer cells motility." (PMID 33308321, 2020). "We investigated the roles of EZH2 and LOXL4 in breast cancer by treating MDA-MB-231 cells with numerous EZH2 inhibitors, such as DZNep, GSK343, UNC1999, or EPZ005687." (PMID 32754259, 2020). "The correlation between EZH2 or NSD2 expression and clinicopathological characteristics of breast cancer (BC)." (PMID 33665162, 2020). "For example, RNF20 represses the oncogene EZH2 in the basal breast cancer cell line HCC1937, while promoting its expression in the luminal breast cancer cell line MCF7." (PMID 30781493, 2019). "The EZH2-H3K27me3-DNMT1 complex orchestrated epigenetic silencing of the wwc1 gene, a Hippo/YAP pathway upstream effector, in breast cancer epithelial cells." (PMID 31271097, 2019). "As inhibition of EZH2/1 and EZH2‐only elicited diametric effects on NKILA expression in the two breast cancer cell lines, we explored the potential contribution of EZH1 to these cell‐specific events." (PMID 31282094, 2019). "EZH2, a known EMT regulator in melanoma, also promotes EMT in breast cancer and induces migration and invasion of renal cancer cells." (PMID 30710146, 2019). "Overexpression of epigenetic repressor EZH2 involve in EMT, self-renewal potential of CSCs, aggressiveness, poor survival, tumor recurrence and resistance in breast cancer." (PMID 35582717, 2019). "In breast cancer and castration resistant prostate cancer, phosphorylation of serine 21 by AKT has been shown to play an essential role in diverting EZH2 away from its function as a histone methyltransferase, although its enzymatic activity was still required." (PMID 31363169, 2019). "We define a novel signaling loop encompassing canonical and non‐canonical actions of EZH2 on the regulation of NF‐κB/NKILA homeostasis, with relevance to breast cancer treatment." (PMID 31282094, 2019). "The co-expression network revealed that ELAVL2, VIM, MRPS12, HSPE1, EZH2, HIST1H4B, and MRPL13 played a vital role in the progression of breast cancer, and we further selected important modules of target genes through MCODE." (PMID 30881302, 2019). "Enhancer of zeste homolog 2 (EZH2), is the catalytic component of the polycomb repressive complex 2 (PRC2) and is highly expressed in breast cancer." (PMID 31252590, 2019). "Here, we investigated the interaction between EZH2 and the NF‐κB/NKILA signaling axis in a non‐tumourigenic breast epithelial cell line and in two breast cancer cell lines displaying differential hormone receptor expression." (PMID 31282094, 2019). "More to the point, ANCR is necessary for the binding of CDK1 to EZH2, where CDK1 marks EZH2 for ubiquitin-proteasome degradation via Thr-345 and Thr-487 phosphorylation in breast cancer cells." (PMID 31658672, 2019). "HOTAIR, the most studied lncRNA, interacts with 26 various functional elements, such as EZH2 and PCBP1, and 40 diseases, including gastric cancer, breast cancer and colon cancer." (PMID 30759219, 2019). "Our evaluation of homeostatic levels of EZH2, NF‐κB and NKILA corresponds to expression levels established in previous studies of breast cancer cell lines and patient‐derived tumours." (PMID 31282094, 2019). "The study of the interaction between LINC00511 and EZH2, the catalytic subunit of PRC2, was a crucial step towards understanding the mechanisms through which LINC00511 exerted its oncogenic function in breast cancer." (PMID 31395854, 2019).
breast cancer (continued). "ChIP analysis revealed that EZH2 can directly bind to SOX4 promoter regions and induce trimethylation of H3K27 in breast cancer cells." (PMID 31557401, 2019). "Consistently, targeting the catalytic subunit of the PRC2 complex, Enhancer of Zeste Homolog 2 (EZH2), led to the de-depression of enhancers controlling the pro-apoptotic B cell lymphoma-2 like 11 (BIM), thereby mediating apoptosis in breast cancer cells." (PMID 31067678, 2019). "Partial silencing of NKILA significantly increased NF‐κB, EZH2 and H3K27 methylation in both breast cancer cell lines." (PMID 31282094, 2019). "Two structurally unrelated Ezh2 inhibitors, GSK126 and EPZ643853, also significantly impaired the proliferation of ErbB2-driven breast cancer cells in vitro." (PMID 31263101, 2019). "In Tamoxifen-resistant breast cancer tissues, the GREB1 promoter becomes more methylated via the action of the histone lysine N-methyltransferase EZH2, leading to the epigenetic downregulation of GREB1." (PMID 30154312, 2018). "The mRNA and protein expression of EZH2 and SMYD3 in normal breast epithelial cells MCF-10A and breast cancer cells MCF-7, MDA-MB-231, T47D, and Bcap-37 were detected by RT-qPCR and Western blotting." (PMID 29089464, 2018). "We have reported enhancer of zeste homolog 2 (EZH2)-mediated H3-K27-me3 and H3-K9-me3 motifs in the RKIP promoter of prostate and breast cancer cell lines." (PMID 30149591, 2018). "Using EZH2 inhibitor DZNepA and EZH2si in NIC-treated breast cancer cells, involvement of EZH2 in NIC-mediated aggressiveness of the disease was evaluated." (PMID 29396474, 2018). "On the contrary, in the ER-positive breast cancer cell line, MCF-7, EZH2 interacted with ER and activated the recruitment of the PRC2 complex on the NF-κB promoter where EZH2 tri-methylated H3K27 and repressed NF-κB transcription." (PMID 34991274, 2018). "The results showed that the mRNA and protein expression of EZH2 and SMYD3 in breast cancer cells MCF-7, MDA-MB-231, T47D, and Bcap-37 were higher than those in normal breast epithelial cells MCF-10A (P<0.05)." (PMID 29089464, 2018). "Reverse-transcription quantitative PCR (RT-qPCR) and Western blotting were used to examine EZH2 and SMYD3 expression in breast cancer tissues and cells." (PMID 29089464, 2018). "We used data from other breast cancer cell line studies of MCF7 and MDA-MB-231 to classify a subset of PRC target genes based on H3K27me3 enrichment or binding of EZH2, an enzyme that generates the H3K27me3 mark." (PMID 30253781, 2018). "EZH2 is involved in regulation of cell cycle progression and dysregulation of EZH2 accelerates cell proliferation and promotes survival, resulting in cancer development, such as CRC, melanoma and breast cancer." (PMID 29556394, 2018). "Second, in the breast cancer cell lines—MDA-MB-468, MDA-MB-231, and SKBr3—the MEK-ERK1/2 pathway activated EZH2 transcription via the direct recruitment of P-ELK1 on the EZH2 promoter." (PMID 34991274, 2018). "Overall, H3K27me3 and EZH2 enrichments from two breast cancer cell lines (MCF7 and MDA-MB-231) correspond to relatively low expression in all three breast cancer cell lines studied here." (PMID 30253781, 2018). "Our results confirmed the role of EZH2 in regulation of FOXA1 and FOXC1 expression in breast cancer cells but the effect of EZH2 depletion on these genes expression was cell- dependent." (PMID 29864144, 2018). "To interrogate further correlations between FOXC1, EZH2 and downstream FOXC1 targets at the protein level in human breast cancer, we made use of recently published proteomic analysis of a subset of TCGA breast cancer patients." (PMID 29959321, 2018). "Using TCGA breast cancer dataset, we found that CUL1 mRNA levels positively correlated with EZH2 mRNA expression." (PMID 30578411, 2018). "To explore this, we first analysed EZH2 and FOXC1 transcript levels in a large cohort of breast cancer patient data from The Cancer Genome Atlas (TCGA) database." (PMID 29959321, 2018).
breast cancer (continued). "While Ezh2 up-regulation was initially associated with aggressive breast cancers, several studies now indicate that Ezh2 overexpression may be a consequence rather than a cause of breast cancer." (PMID 30080881, 2018). "Furthermore, protein levels corresponding to FOXC1 target genes were lower in Luminal B patients with high EZH2 and low FOXC1 expression, supporting our hypothesis that a FOXC1-driven transcriptional program is suppressed by EZH2 specifically in Luminal B breast cancer." (PMID 29959321, 2018). "Similarly, EZH2 is also found to act as a co-activator of other critical transcription factors, such as TCF/β-catenin and the DNA repair protein PCNA-associated factor in colorectal cancer (CRC), β-catenin and ERα in breast cancer, to promote the transcription of their target genes, respectively." (PMID 29556394, 2018). "In this study, we determined the impact of OGT on expression of EZH2 target genes FOXA1 and FOXC1, that are involved in breast cancer progression." (PMID 29864144, 2018). "The upregulation in EZH2, which is due to NIC, was further confirmed in breast carcinoma cell lines using 10 μM NIC, 1 μM DZNepA, and EZH2si." (PMID 29396474, 2018). "A correlation between the expression of EZH2 and HOTAIR in breast cancer was observed in a high throughput tissue microarray study." (PMID 29469819, 2017). "Recent research supports that EZH2 overexpression and CSC expansion can result in the progression of breast cancer." (PMID 28415635, 2017). "We assessed the clinicopathological significance of EZH2 expression in MBC according to subtype; however, the number of breast cancer patients for each subtype was too small to show statistical significance." (PMID 28241804, 2017). "Another study reports that downregulation of EZH2 results in significant increases in CIITA and HLA-DRA expression as well as increased cell surface expression of MHC II in breast cancer." (PMID 29132376, 2017). "Relative to a role in cancer, EZH2 functions to promote self-renewal and has been shown to be important for the tumor-initiating cell (TIC) phenotype in breast cancer." (PMID 27764181, 2016). "GSK343, the potent and selective inhibitor of EZH2, was recently discovered and reported to selectively reduce trimethylated H3K27 (H3K27me3) and inhibit breast cancer cell proliferation in cell-based studies." (PMID 26868841, 2016). "EZH2 was found to activate Notch1 and RAF1-β-catenin signaling in breast cancer to promote self-renewal." (PMID 27764181, 2016). "The effect of metformin treatment on breast cancer cell viability and miR-26a, BCL-2, PTEN, MCL-1, EZH2, and MTDH modulation were evaluated." (PMID 27517917, 2016). "It was also found that EZH2 interacts with RelA/RelB complex co-regulating a subset of NF-κB targets independently of PRC2, and increasing the aggressiveness of breast cancer cells." (PMID 27793053, 2016). "Metformin treatment reduced breast cancer cell viability, increased miR-26a expression, and led to a reduction in BCL-2, EZH2, and PTEN expression." (PMID 27517917, 2016). "However, based on recent evidence showing that EZH2 can be transcriptionally induced by estrogen in breast cancer cells, this might provide a mechanism by which the methylation of H3K27 can be promoted by estrogen in conjunction with the direct recruitment of ERα at the HYAL1 ERE-900." (PMID 27764788, 2016). "We and others have shown that Fra-1 promotes metastasis through various molecules: ADORA2B in breast cancer, MMPs in breast cancer and in lung epithelial cells, CD44 in mesothelioma, AXL in bladder cancer, FAK and EZH2 in colon cancer." (PMID 26646695, 2015). "Accordingly, we identified the interaction between EZH2 and TFIIIC102 in another breast cancer cell line SUM159, suggesting that the interaction between EZH2 and TFIIIC102 occurs widely in breast cancer cells." (PMID 26038315, 2015).